IGF1 (insulin like growth factor 1)
Diseases named in the same sentence as IGF1 in open-access papers (continued):
Sharing a sentence is not in itself a finding about the gene and the disease.
acromegaly (continued). "Twenty-three of the total number of acromegaly patients were treatment-naïve, whereas thirty-six were treated, though uncontrolled (i.e., IGF-1 levels remained elevated, at 1.3 times the upper limit of normal (ULN))." (PMID 41596725, 2026). "The observed increase in saturated species such as SM 34:0;O2 alongside the decrease of polyunsaturated species, e.g., SM 34:2;O2 in the serum of acromegaly patients underpins complex lipid metabolism disturbances induced by GH/IGF-1 excess." (PMID 41596725, 2026). "Acromegaly is a rare, yet serious disorder resulting from the chronic hypersecretion of growth hormone (GH) and insulin-like growth factor-1 (IGF-1), most commonly due to pituitary adenomas." (PMID 41358366, 2026). "The increased cancer risk in acromegalic patients did not correlate with age, sex, age at diagnosis, time to diagnosing acromegaly, duration of acromegaly, GH and IGF-1 levels at diagnosis, pituitary adenoma size, or Ki-67 levels." (PMID 41753260, 2026). "This study provides a comprehensive characterization of functional brain alterations in patients with acromegaly at rest, revealing distinct network‐level signatures of chronic GH/IGF‐1 excess." (PMID 41550023, 2026). "Active acromegaly was diagnosed based on elevated serum insulin-like growth factor 1 (IGF-1) (>1× upper limit of normal) or insufficient GH suppression (nadir ≥0.4 ng/mL) during an OGTT." (PMID 41488995, 2026). "The aim of this narrative review is to summarize the nutritional regulation of the GH/IGF-1 axis and synthesize the evidence on how macronutrients and different dietary regimens affect biochemical control and comorbidity management in acromegaly." (PMID 41472889, 2026). "An initial evaluation revealed a pituitary macroadenoma measuring 19x17x16 mm, with elevated GH and insulin-like growth factor-1 (IGF-1) levels, consistent with acromegaly." (PMID 41358366, 2026). "The clinical presentation of acromegaly reflects systemic effects of chronic growth hormone (GH) and insulin-like growth factor 1 (IGF-I) excess." (PMID 42056759, 2026). "IGF-1 testing should be reserved for patients exhibiting clinical features or phenotypic suspicion of acromegaly." (PMID 41878803, 2026). "In the course of acromegaly, chronic GH and IGF-1 excess lead to unfavorable changes in bone microstructure, despite the frequent presence of increased bone mass." (PMID 41295066, 2025). "The low IGF-1 levels in our patient, despite normal pituitary imaging, emphasize the need for careful differentiation from acromegaly." (PMID 41552116, 2025). "Normalization of IGF1 and reduction of GH levels (< 2.5 μg/L) reverses the excess mortality seen in untreated acromegaly to that of the general population." (PMID 39959623, 2025). "Osseointegration of dental implants in patients with acromegaly is feasible, as confirmed by both preclinical data (animal models, GH/IGF-1 application) and isolated clinical observations." (PMID 41295066, 2025). "Disease control by reduction of IGF-1 levels has been shown to result in a decrease in acromegaly-related mortality to that experienced by the general population." (PMID 40672042, 2025). "Twelve months after the beginning of acromegaly treatment, IGF-1 levels decreased significantly (p < 0.001), and biochemical control of disease was achieved in 73.52% of APs." (PMID 40429391, 2025). "Acromegaly, a rare endocrine disorder characterised by excess growth hormone (GH) and insulin-like growth factor 1 (IGF-1), is often due to GH-secreting pituitary adenomas." (PMID 41287839, 2025). "Acromegaly presents as a chronic endocrine disorder characterised by hypersecretion of growth hormone (GH) and insulin-like growth factor-1 (IGF-1), primarily induced by a GH-secreting pituitary adenoma." (PMID 41353330, 2025). "The correlation found between the LVM/LVMI and IGF-1 highlights the significant effect of IGF-1 in LVH pathogenesis in acromegaly." (PMID 40429391, 2025).
acromegaly (continued). "The diagnosis of acromegaly was confirmed, defined by IGF-1 > 1.3 times the upper limit of normal for age in a patient with typical signs and symptoms of acromegaly." (PMID 41220589, 2025). "While direct investigations into angiogenesis at implant sites in acromegaly are scarce, it is well established that GH and IGF-1 play critical roles in stimulating endothelial cells, thereby promoting new vessel formation." (PMID 41295066, 2025). "Hormonal evaluation revealed low insulin-like growth factor-1 (IGF-1) levels with normal pituitary imaging, effectively excluding acromegaly." (PMID 41552116, 2025). "A current therapeutic approach to acromegaly should aim not only for the biochemical normalization of IGF1 levels but also for optimal control of comorbidities and complications." (PMID 39821533, 2025). "Acromegaly is characterized by high levels of growth hormone (GH), which in turn leads to the secretion of insulin-like growth factor-1 (IGF-1), with a prevalence of 4,600 per million." (PMID 41589173, 2025). "Based on these findings, a multivariable logistic regression model was conducted to analyze the predictive factors for the presence of colon polyps in acromegaly, including age, sex, DM, and basal IGF-1 and GH levels." (PMID 40167828, 2025). "Higher levels of IGF-1/GH correlate with comorbidities of acromegaly, including cardiomyopathy, making earlier diagnosis of acromegaly a priority in care." (PMID 40697972, 2025). "Acromegaly patients can be classified as active or in biochemical remission based on GH and IGF-1 levels." (PMID 40725515, 2025). "Excess GH and IGF-1 in acromegaly can lead to so-called acromegalic cardiomyopathy, a clinical picture characterized by concentric biventricular hypertrophy and diastolic dysfunction." (PMID 40142714, 2025). "For the first time, we found that acromegaly patients with PIT1/SF1 tumors had significantly higher baseline IGF-1 levels than patients with PIT1 tumors." (PMID 40421250, 2025). "The observed increase in macroglossia and fissured tongue among patients with acromegaly can be attributed to the chronic exposure to elevated levels of GH and IGF-1." (PMID 41353330, 2025). "After surgery, biochemical control of acromegaly improved with IGF-1 and prolactin within the normal range and OGTT GH nadir of 0.6 ug/L." (PMID 40357201, 2025). "Diagnosis of coexisting growth hormone excess is often overlooked, not only due to the dual effects on growth but also because IGF-1—an indicator of growth hormone excess—becomes unreliable in the context of concurrent precocious puberty." (PMID 40917355, 2025). "Although reductions in GH/IGF-1 levels can alleviate the severity of sleep apnea, up to 40% of acromegaly patients still experience persistent sleep apnea." (PMID 40727910, 2025). "Acromegaly is a rare condition resulting from growth hormone (GH) and insulin-like growth factor-1 (IGF-1) excess." (PMID 40091946, 2025). "It is important to note that the last report from our center showed an overall control rate in patients with acromegaly of 52% based on IGF-1 measurement." (PMID 39425840, 2025). "In most studies, patients reported subjective improvement in symptoms related to acromegaly, and levels of growth hormone and insulin-like growth factor-1 (IGF-1) were found to be suppressed." (PMID 40384778, 2025). "Intraindividual, week-to-week variation in IGF-1 levels has been reported to impact the assessment of biochemical control in acromegaly patients." (PMID 39378125, 2025). "The diagnosis of acromegaly was confirmed via clinical features, persistent IGF-1 elevation, pituitary imaging, and definitive pathological evidence of a densely granulated GH-secreting adenoma." (PMID 40842744, 2025). "The suspicion of acromegaly must be confirmed by blood tests, including the determination of GH and IGF-1 levels following an oral glucose tolerance test, as well as a magnetic resonance imaging (MRI) study of the pituitary gland." (PMID 41567317, 2025).
acromegaly (continued). "When comparing baseline IGF-1 levels with the biochemical control of acromegaly immediately before PAS therapy, the entire cohort exhibited a median reduction of −51% in IGF-1 levels (from 753 μg/L to 416 μg/L; p < 0.001)." (PMID 39841390, 2025). "Acromegaly is a rare condition characterized by excessive secretion of growth hormone (GH) and insulin-like growth factor 1 (IGF-1)." (PMID 41234959, 2025). "Crucially, our dedicated subgroup analysis revealed that in patients with acromegaly, disease activity (IGF-1 levels) is a significant predictor of worse myocardial strain, providing a powerful, disease-specific insight." (PMID 41307388, 2025). "Our study shows that the predictors of surgical failure and fgSRLs resistance in patients with GH&PRL-PAs are similar to those observed in acromegaly with GH-PAs, including Knosp grade and serum GH and IGF-1 levels at diagnosis as key factors." (PMID 40590355, 2025). "Acromegaly is a chronic systemic disease characterized by elevated growth hormone (GH) and insulin-like growth factor 1 (IGF-1) levels." (PMID 40421250, 2025). "Acromegaly is a rare and slowly progressive condition, resulting from chronic exposure to excess GH and, consequently, IGF-1, leading to somatic, metabolic, and cardiovascular alterations." (PMID 41458762, 2025). "Responsive acromegaly patients, often have smaller intra-sellar tumors, with lower GH and IGF-1 levels and a low proliferation rate." (PMID 39841390, 2025). "Acromegaly, characterized by excessive GH and insulin-like growth factor-1 (IGF-1), impacts quality of life (QoL) and mortality." (PMID 39378125, 2025). "In patients with acromegaly, chronic exposure to excess growth hormone and IGF-1 alters bone metabolism and remodeling, leading to cortical thickening, disrupted trabecular organization, and increased bone turnover." (PMID 41295066, 2025). "OSAHS is a prevalent comorbidity in patients with acromegaly, with hormonal factors such as elevated IGF-1 and GH levels playing a critical role in its pathogenesis." (PMID 39958072, 2025). "In acromegaly, increased IGF-1 levels lead to reduced endothelial NOS expression, resulting in decreased serum NO levels." (PMID 40186831, 2025). "Nowadays, IGF-1 indicates that GH production is applied as an essential scale of remission and presents the outcome of the medical interventions in acromegaly." (PMID 41334063, 2025). "In our study, 12 months after the beginning of acromegaly treatment, IGF-1 levels decreased significantly (p < 0.001) and biochemical control of disease was achieved in 73.52% of APs." (PMID 40429391, 2025). "This elevated risk of complications was found to be higher compared to the general population before the diagnosis of acromegaly was made, suggesting that chronic exposure to excess GH and IGF-1 contributes to a prothrombotic state." (PMID 41234959, 2025). "A key finding from a dedicated acromegaly subgroup analysis was that disease activity (IGF-1) independently predicted impaired GLS." (PMID 41307388, 2025). "Studies have confirmed that successful acromegaly treatment tends to increase fat mass, while lean mass decreases, which can be attributed to changes in metabolic processes due to declining GH/IGF-1 levels." (PMID 40429391, 2025). "Acromegaly is a rare endocrine disease characterized by elevated serum growth hormone (GH) and insulin-like growth factor-1 (IGF-1) levels, usually originating from a pituitary adenoma." (PMID 40186831, 2025). "Here, we report the case of a patient with acromegaly and a substantial disease burden, reflected by markedly elevated insulin-like growth factor 1 (IGF-1) levels and multiple severe comorbidities, who presented with spontaneous bilateral lens luxation (LL)." (PMID 41220589, 2025). "In all five cases switching to pasireotide demonstrated marked efficacy by normalising IGF-1 and eliminating acromegaly symptoms within the first months of treatment." (PMID 41287839, 2025).
acromegaly (continued). "Acromegaly is characterized by excess growth hormone (GH) and insulin-like growth factor-1 (IGF-1) production." (PMID 40672042, 2025). "Acromegaly is a slowly progressive disease resulting from the increased release of growth hormone (GH) and, consequently, Insulin- like growth factor 1 (IGF-I) induced in most cases by a GH-secreting pituitary adenoma." (PMID 41071261, 2025). "Acromegaly is a rare disorder due to the excessive secretion of GH from the pituitary gland, which results in high levels of IGF-1." (PMID 40791994, 2025). "Acromegaly is a rare disease resulting from excess growth hormone (GH) and insulin-like growth factor-1 (IGF1), with cardiovascular complications being frequently encountered, leading to increased morbidity and mortality." (PMID 40091946, 2025). "Patient 1, a 39-year-old male with hyperprolactinaemi+a and acromegaly who underwent multiple therapies including surgery and radiotherapy, showed tumour size reduction and IGF-1 control with pasireotide." (PMID 41287839, 2025). "Laboratory workup confirmed acromegaly with concomitant hyperprolactinemia (IGF-1 level was 1.5x the upper limit of normal range (NR))." (PMID 40357201, 2025). "The altered GH/IGF-1 axis in acromegaly results in various cardiovascular, respiratory, and metabolic complications." (PMID 40091946, 2025). "Clinical outcomes were favorable in the majority of cases, with normalization of GH and IGF-1 levels in 11 patients and partial remission of acromegaly in six others." (PMID 41573472, 2025). "Acromegaly is a chronic disease characterized by the overproduction of growth hormone (GH), resulting in elevated levels of insulin-like growth factor 1 (IGF-I)." (PMID 40622518, 2025). "To assess AcroFace’s ability to identify non-acromegaly cases, we tested it on a control dataset of 56 facial images from healthy individuals with normal IGF1 levels." (PMID 40257631, 2025). "Here, we describe a case of a patient with acromegaly in remission for 25 years who presented with cardiac symptoms and was diagnosed with hypertrophic cardiomyopathy while GH/IGF-1 levels were normal." (PMID 40697972, 2025). "Acromegaly treatment aims to normalize plasma GH and IGF-1 levels using surgery, medical treatment, or radiotherapy." (PMID 39859181, 2025). "Acromegaly is a rare endocrine disorder characterized by chronic excess growth hormone (GH) and elevated insulin-like growth factor-1 (IGF-1), which are known to have mitogenic and anti-apoptotic effects on breast tissue." (PMID 41293738, 2025). "Current consensus on criteria for acromegaly diagnosis and remission recommends assessing IGF-1 levels at 3 months after therapy initiation, followed by evaluations every 6–12 months after biochemical control is achieved." (PMID 41220589, 2025). "Acromegaly is a chronic disease characterized by the excessive production of growth hormone (GH), resulting in elevated levels of insulin-like growth factor-1 (IGF-1)." (PMID 40142714, 2025). "It is notable in this case that four physicians dismissed the diagnosis of acromegaly, which was made only because the patient, who was in the medical field, persisted in pursuing GH and IGF-1 testing." (PMID 40697972, 2025). "In our acromegaly cohort, 66% had IGF-1 levels within the reference range, but 77% were assessed as biochemically controlled by an experienced endocrinologist based on full clinical, biochemical, and radiological assessment at the including center." (PMID 39363748, 2025). "Acromegaly treatments aim to normalize plasma GH and IGF-1 concentrations, improving insulin resistance and reducing gluconeogenesis." (PMID 39859181, 2025). "Acromegaly, most commonly due to a pituitary growth hormone (GH)-secreting adenoma, is characterized by chronic excess of GH and insulin-like growth factor-1 (IGF-1)." (PMID 41302934, 2025).
acromegaly (continued). "The pathophysiology of acromegaly extends beyond the direct effects of elevated growth hormone and IGF-1 levels; it also encompasses a range of pathological changes that increase the risk of serious health complications." (PMID 40142714, 2025). "Subsequent investigations revealed a 15-mm pituitary adenoma, along with biochemical evidence of massive growth hormone hypersecretion (Growth Hormone (GH): 93.22 μg/L; insulin-like growth factor 1 [IGF-1]: 748 μg/L), consistent with acromegaly." (PMID 41220589, 2025). "IGF-1 is considered the most reliable biomarker of disease activity for patients with acromegaly and the dominant driver for treatment decisions." (PMID 39378125, 2025). "Large-scale population studies outside of acromegaly consistently reinforce the role of IGF-1 in breast carcinogenesis." (PMID 41293738, 2025). "Acromegaly treatment, through lowering plasma GH and IGF-1 concentrations, should lead to an improvement in glucose metabolism." (PMID 39859181, 2025). "In spite of the small number of patients participating in this trial, strict control in acromegaly patients with modest IGF1 elevations by PEGV initiation or dose escalation was accompanied by clinical improvements detected by the PASQ score." (PMID 39959623, 2025). "A study in 358 medically-naïve patients with acromegaly, pasireotide vs. octreotide achieved normal GH levels (31% vs. 19%), and normal IGF-1 levels (35% vs. 20%)." (PMID 41287839, 2025). "Previous studies have shown that cognitive impairment is highly prevalent in patients with acromegaly, and its severity correlates with elevated levels of GH and IGF-1." (PMID 41470032, 2025). "Given the clinical suspicion of acromegaly, serum IGF-1 was measured and found to be elevated at more than four times the upper limit of normal." (PMID 41573472, 2025). "Chronic GH/IGF-1 excess in acromegaly increases bone turnover and induces persistent microarchitectural deficits—reduced trabecular number, increased trabecular separation, and elevated cortical porosity—often despite normal or elevated aBMD." (PMID 41295066, 2025). "The measurements of tongue volume have demonstrated positive relationships with BMI and IGF-1 levels in patients who received treatment and those who had active acromegaly." (PMID 40791994, 2025). "The diagnosis was confirmed considering the subtle features of acromegaly combined with the high IGF-1 when her pituitary function was assessed." (PMID 41287839, 2025). "Given that pretreatment IGF-1 levels are important predictors of morbidity and mortality in acromegaly, our patient not only experienced prolonged exposure to elevated IGF-1 and a high disease burden but was also ineligible for first-line therapy." (PMID 41220589, 2025). "For the evaluation of biochemical control of the disease, 74 (71.8%) patients reached biochemical control of acromegaly (IGF-1 ≤ ULN) with multimodal treatment during their follow-up, whereas 15 patients (14.6%) did not." (PMID 39987353, 2025). "After effective treatment, cardiac abnormalities in acromegaly are reversible to a normal state, especially in young patients with short disease duration and GH/IGF-1 levels under control." (PMID 40429391, 2025). "In patients with acromegaly and modest IGF1 elevation, strict IGF1 control was achieved by addition or dose escalation of pegvisomant." (PMID 39959623, 2025). "For patients with acromegaly, serum GH and serum insulin‐like growth factor‐1 (IGF‐1) levels should be measured at least 12 weeks after surgery." (PMID 40546879, 2025). "The prevalence of goiter in individuals with acromegaly indicates a considerable role of IGF-1 in the growth of the thyroid gland." (PMID 38455769, 2024). "As a result, he was diagnosed with acromegaly showing elevated GH and insulin-like growth factor-1 (IGF-1) with a pituitary tumor." (PMID 38765413, 2024).